ALK (ALK receptor tyrosine kinase)
Diseases named in the same sentence as ALK in open-access papers (continued):
Sharing a sentence is not in itself a finding about the gene and the disease.
lung adenocarcinoma (continued). "We report a patient with a long-standing history of leptomeningeal disease due to ALK-positive adenocarcinoma of the lung, previously controlled by increased doses of lorlatinib (125 mg/day)." (PMID 39688636, 2024). "The CK5‐positivity rate was significantly higher in ALK‐positive lung adenocarcinomas compared with the wild‐type (WT) and was significantly lower in EGFR‐positive lung adenocarcinomas compared with the WT." (PMID 38400801, 2024). "In conclusion, this case report described a novel ALK double-fusion involving PLEKHA7-ALK and INPP5D-ALK in lung adenocarcinoma." (PMID 38379102, 2024). "Approximately, 25% of lung adenocarcinoma patients have targetable driver mutation including EGFR, ALK, ROS-1, BRAF, MET, and cErbB2." (PMID 38668879, 2024). "Another controversial finding was in the field of lung adenocarcinoma, where it was found that PTK7 expression correlates with lymph node metastasis, and that high PTK7 expression implies a higher rate of ALK mutation and a lower rate of EGFR mutation." (PMID 39474113, 2024). "For instance, patients affected by lung adenocarcinoma are commonly screened for ALK rearrangements to identify potential candidates for ALK inhibitors (approximately 4% of NSCLC patients)." (PMID 38015944, 2023). "Patients with anaplastic lymphoma kinase (ALK) fusion gene rearrangement account for 2–4% of lung adenocarcinoma." (PMID 37749521, 2023). "Fusion EML4:ALK, a known cancer driver prevalent in lung adenocarcinoma, has evidence of multiple transcript variant structures, and while microhomologies are found between the EML4 and ALK genes they tend to be distal from the fusion variant breakpoints." (PMID 37323575, 2023). "Within the scope of this study, we present a noteworthy discovery: the identification of an unreported fusion involving KIF13A and ALK in a patient with lung adenocarcinoma." (PMID 38155713, 2023). "Another study reported one lung adenocarcinoma patient with EML4‐ALK fusion developed MET‐KDD as a new resistance mechanism for ALK inhibitor ceritinib." (PMID 36325957, 2023). "Herein, firstly, we report two cases of resectable ALK-positive lung adenocarcinoma receiving more than six months of alectinib as neoadjuvant therapy followed by radical surgical resection to achieve pathological complete responses." (PMID 37409244, 2023). "We report two cases of lung adenocarcinoma with resectable ALK-positive that achieved pCR with long-course neoadjuvant alectinib." (PMID 37409244, 2023). "The prevalence of Anaplastic Lymphoma Kinase gene (ALK) fusion is about 5% among patients with lung adenocarcinoma, underscoring the importance of pinpointing distinct fusion variants for optimizing treatment approaches." (PMID 38155713, 2023). "Multiple genetic alterations have been identified as therapeutic targets in lung adenocarcinoma, including mutations in EGFR, ERBB2, BRAF, KRAS, and MET and rearrangements of ALK, RET, and ROS1." (PMID 37628603, 2023). "Further investigations for the first-line treatment of ALK-positive smoking advanced lung adenocarcinoma patients are needed." (PMID 37007097, 2023). "This proteomic assay was used to identify proteins related to HSP90 inhibition responsiveness according to the most relevant molecular alteration in lung adenocarcinoma such as EGFR and KRAS mutations and ALK translocation." (PMID 37762133, 2023). "Endoscopic biopsy of the left pleural tissue suggested lung adenocarcinoma with ALK-Ventana D5F3, keratin 7, napsin A and thyroid transcription factor-1 (TTF-1) positivity, and adenocarcinoma cells were also found in pleural effusion and pericardial effusion." (PMID 37055606, 2023). "Findings in this case indicated a primary lung adenocarcinoma with ALK gene rearrangement, in which an SRCC component accounted for approximately 95% of the tumor." (PMID 37842503, 2023). "The patient was diagnosed with primary lung adenocarcinoma, and ALK rearrangement was detected during second-line chemotherapy." (PMID 37122027, 2023).
lung adenocarcinoma (continued). "Summary of reported cases receiving neoadjuvant alectinib therapy in ALK-positive lung adenocarcinoma." (PMID 37409244, 2023). "We present two cases of resectable ALK-positive lung adenocarcinoma that had a pCR following long-course neoadjuvant alectinib treatment." (PMID 37409244, 2023). "EGFR, ALK, BRAF, KRAS, ROS1 are the five common genes in lung adenocarcinoma, and EGFR gene mutation is the most common." (PMID 37340599, 2023). "It is a novel class of multikinase inhibitors, the ALK inhibitors which are most effective in ALK-fusion positive lung adenocarcinoma." (PMID 36213163, 2022). "Similar observations have been made in ALK+ lung adenocarcinoma: Also here, the main resistance mechanisms to next-line lorlatinib are compound ALK mutations, which affect ∼30% of patients and are facilitated by previous treatment with second-generation drugs." (PMID 36207130, 2022). "This lesion had a cribriform architecture, which is the most common morphology seen in ALK-positive lung adenocarcinomas, suggesting at least some lineage-independent overlap of histomorphologic features in cases with ALK alterations." (PMID 36337169, 2022). "We present the first case of a rare SLC8A1 downstream intergenic region of ALK fusion in an advanced lung adenocarcinoma patient treated effectively with ceritinib using powerful NGS." (PMID 36042596, 2022). "We provide evidence that patient with lung adenocarcinoma with ALK-HLA-DRB1 rearrangement shows impressive progression-free survival after sequential crizotinib and ceritinib treatment." (PMID 35280798, 2022). "In this case report, we identified a novel non-reciprocal ALK fusion: ALK-grancalcin (GCA) (A19: intragenic) and EML4-ALK (E20: A20) by next-generation sequencing (NGS) in a male lung adenocarcinoma patient who was staged as IIIB-N2 after surgery." (PMID 35070986, 2022). "In July 2015, a 60-year-old woman was diagnosed with stage IV lung adenocarcinoma with ALK gene rearrangement." (PMID 35727390, 2022). "In the present study, detection of ALK gene rearrangements in lung adenocarcinoma cases was carried out using ICC on cell-blocks." (PMID 34514573, 2022). "Despite a more aggressive course than typical for ALK+ lung adenocarcinoma, our ALK+ LCNEC patient derived significant benefit from targeted and local therapies and achieved an OS of >3 yr." (PMID 36207130, 2022). "Common driver mutations (EGFR, ALK, BRAF, ERBB2, KRAS, MET, RET, and ROS1) analysis were performed in lung adenocarcinoma tissue samples from two PEAC patients (P08 and P10) using next-generation sequencing." (PMID 35172862, 2022). "Our interest in this case arose from the fact that this case is the first report of a durable, dramatic response to alectinib in a lung adenocarcinoma patient harboring both an EGFR mutation and an ALK rearrangement for the uncommon genomic breakpoint." (PMID 36107507, 2022). "Molecular targeting therapy is becoming the standard of care for some patients with anaplastic lymphoma kinase (ALK)-rearranged lung adenocarcinoma." (PMID 36386178, 2022). "Using DNA sequencing, we identified a novel ALK-RAB10 rearrangement within a lung adenocarcinoma patient that is actually a canonical ALK fusion at the transcript level." (PMID 36107507, 2022). "Then, we comprehensively depicted the TIME of ALK+ tumors using our surgically resected lung adenocarcinoma (LUAD) specimens." (PMID 36233802, 2022). "All 9 patients with EGFR- or ALK-positive lung adenocarcinomas received a treatment with tyrosine kinase inhibitors (TKIs) before and/or after brain radiation therapy." (PMID 36199814, 2022). "In our case, a novel CLHC1/RNT4 intergenic region, ALK fusion, was identified for the first time in a lung adenocarcinoma patient with BM, who benefited from crizotinib and endostar sequential alectinib." (PMID 35446297, 2022).
lung adenocarcinoma (continued). "Immunocytochemistry on cell-blocks using the DF53 clone is a highly sensitive and specific method for detection of ALK gene rearrangements in lung adenocarcinoma with greater number of ALK positive cases being detected on ICC as compared to ALK-FISH." (PMID 34514573, 2022). "EGFR mutations were more likely to occur in non‐smoking, stage III–IV, and female patients with lung adenocarcinoma, whereas ALK&ROS1 gene fusions were more likely to occur in young patients with lung adenocarcinoma." (PMID 35081265, 2022). "For patients with driver mutations, such as EGFR (10% of NSCLC cases) and BRAF (0.5–4.9% of lung adenocarcinomas), and rearrangements in ROS1 (1–2% of lung adenocarcinomas) and ALK (3–7% of lung adenocarcinomas) gene-targeted therapy can be used." (PMID 35216378, 2022). "Mutational profiling of 200 lung adenocarcinomas in Korean patients identified mutations of EGFR in 60.5%, KRAS in 12%, and translocations in anaplastic lymphoma kinase (ALK), c-ros oncogene 1 (ROS1), and RET proto-oncogene (RET) in 8.5% of cases." (PMID 35399416, 2022). "Since the first discovery of echinoderm microtubule associated protein-like 4 (EML4)-ALK fusion in patients with lung adenocarcinoma in 2007, a variety of ALK fusion partners have been detected." (PMID 36172736, 2022). "In this case, a 55-year-old man was diagnosed with ALK-positive, stage IV lung adenocarcinoma using immunohistochemistry and next generation sequencing (NGS) tests." (PMID 36523965, 2022). "Here, we present our experience with a patient with lung adenocarcinoma with a rare ALK rearrangement who had a remarkable response after ceritinib treatment." (PMID 35978810, 2022). "Transforming rearrangements of the anaplastic lymphoma kinase (ALK) gene are present in 3–6% of lung adenocarcinomas (LUADs), and these tumors are responsive to crizotinib." (PMID 35328282, 2022). "Here, we describe the multidisciplinary treatment and outcome of a stage IV lung adenocarcinoma patient harboring an ALK alteration." (PMID 36523965, 2022). "In another 42-year-old woman, stage IV lung adenocarcinoma with ALK gene rearrangement in left lower lob was diagnosed in March 2017." (PMID 35727390, 2022). "employed SMOTE as subclass imbalance correction technique in their PET/CT radiomics study to predict anaplastic lymphoma kinase (ALK) rearrangement status in lung adenocarcinoma." (PMID 36303841, 2022). "The present case was a lung adenocarcinoma with an ALK-HLA-DRB1 fusion, which consisted of exon 20 of the ALK gene and exon 8 of the HLA-DRB1 gene." (PMID 35280798, 2022). "BRAF non-Val600 mutations and RUNX1T1 amplifications seem to be unusually prevalent and ALK fusions rare in Finnish lung adenocarcinoma patients." (PMID 35964518, 2022). "Commonly mutated genes in lung adenocarcinoma in Eastern populations include EGFR (~60%), KRAS (~11%), and anaplastic lymphoma kinase (ALK; ~2%), and mutations have also been identified in MET (1%), HER2 (~2%), BRAF (~2%), RET (1%–4%), and ROS1 (~2%)." (PMID 35978810, 2022). "Here, we describe a case of advanced lung adenocarcinoma harboring a rare ALK-HLA-DRB1 (major histocompatibility complex, class II, DR beta 1) gene fusion." (PMID 35280798, 2022). "We also discussed the possibility for the future application of alectinib as an ALK-TKI for lung adenocarcinoma patients having an EGFR mutation and an ALK rearrangement (double positive)." (PMID 36107507, 2022). "A total of 66 plasma specimens from 21 metastatic ALK-positive NSCLC lung adenocarcinoma (LUAD) patients were included in this study." (PMID 36461127, 2022). "Patients with EGFR- or ALK-positive lung-adenocarcinoma showed a trend of better OS compared to those with other histopathologies (MST: 37.2 months vs. 14.6 months, p = 0.077) (Table A2)." (PMID 36199814, 2022). "Mutations in ALK and EGFR have caused huge changes in the treatment of patients with lung adenocarcinoma." (PMID 35463955, 2022).
lung adenocarcinoma (continued). "Based on these findings, a diagnosis with ALK-positive lung adenocarcinoma (cT2bN3M1c: stage IVB) was established." (PMID 36626420, 2022). "In univariate analyses, none of the factors, including the histopathological factors (EGFR/ALK-positive lung-adenocarcinoma vs. others), exhibited statistical significance, with the exception of extracranial metastatic status." (PMID 36199814, 2022). "Approximately 5% of lung adenocarcinomas have ALK rearrangement status, which is mutually exclusive with EGFR mutations." (PMID 36338735, 2022). "Here, we report the second case of a patient with metastatic ALK-rearranged lung adenocarcinoma treated with alectinib throughout pregnancy." (PMID 35814861, 2022). "According to the histological subtypes of NSCLC, lung adenocarcinoma (LUAD) and lung squamous carcinoma (LUSC) are associated with different mutational patterns, but are both mainly enriched for KRAS, EGFR, and ALK mutations." (PMID 36508072, 2022). "Anaplastic lymphoma kinase (ALK) gene rearrangements, have been identified in approximately 2-7% of patients with lung adenocarcinoma (LUAD)." (PMID 35144623, 2022). "The frequency of ALK mutation in NSCLC patients is about 5% in the western and about 4.9% in the Asian population, especially higher in lung adenocarcinomas patients (6.0%)." (PMID 33738250, 2021). "For ALK‐positive lung adenocarcinoma patients, univariate analyses revealed that age (p = 0.016), T stage (p = 0.008), N stage (p = 0.001), and AJCC stage (p < 0.001) were statistically significant predictors of tumor‐specific survival." (PMID 34596344, 2021). "A total of 80 ALK‐positive lung adenocarcinoma participants were included in univariate and multivariate analyses to verify survival factors." (PMID 34596344, 2021). "ALK rearranged lung adenocarcinoma patients who have undergone radical surgery have distinct clinical features." (PMID 34596344, 2021). "Certain clinical and imaging features derived from ALK/ROS1/RET fusion-positive lung adenocarcinoma patients were found to be good discriminators of fusion-positive and fusion- negative lung adenocarcinomas." (PMID 34164563, 2021). "ALK rearrangements at exon 19, instead of usual site within intron 19 or exon 20, has only been rarely described in malignant stromal sarcoma and lung adenocarcinoma before." (PMID 34657620, 2021). "The advanced ALK fusion positive lung adenocarcinoma patients, though the first-line and the second-line chemotherapy, and the follwing application of ALK-TKI treatment, has procured a total OS has reached 68 months, and the current follow-up is good." (PMID 34344501, 2021). "In clinical practice, the mutation/expression of epidermal growth factor receptor (EGFR) and anaplastic lymphoma kinase (ALK) in first-line targeted therapy improves the survival rate of patients with lung adenocarcinoma." (PMID 33446784, 2021). "Patients with lung adenocarcinoma harboring EML4-ALK rearrangements respond well to multiple ALK tyrosine kinase inhibitors (TKIs)." (PMID 33663128, 2021). "Mutational profiling of lung adenocarcinoma patients reveals Kirsten rat sarcoma viral oncogene (KRAS), epidermal growth factor receptor (EGFR), and anaplastic lymphoma kinase (ALK) as the most prominent oncogenic drivers." (PMID 34073823, 2021). "In conclusion, this study highlights the feasibility of non-invasively detecting ALK genetic status in lung adenocarcinomas using a machine learning model based on combined PET/CT radiomic features and clinical characteristics." (PMID 33738250, 2021). "This study intended to non-invasively predict the ALK rearrangement status in lung adenocarcinomas by developing a machine learning model that combines PET/CT radiomic features and clinical characteristics." (PMID 33738250, 2021).
lung adenocarcinoma (continued). "Alectinib should be considered the standard of care in first-line ALK-positive advanced NSCLC, as it was safer and more effective than crizotinib as a first-line chemotherapeutic treatment for patients with ALK-rearranged lung adenocarcinoma." (PMID 34063424, 2021). "In conclusion, we analyzed the potential molecular mechanisms of drug resistance in a lung adenocarcinoma patient with ALK rearrangement following sequential ALK-TKIs treatment." (PMID 33663128, 2021). "A patient with right lung adenocarcinoma harboring an ALK rearrangement received targeted therapy with multiple ALK-TKIs." (PMID 33663128, 2021). "Based on published studies for patients with lung adenocarcinoma who have undergone surgery, the prognostic value of ALK rearrangement in early‐stage lung adenocarcinoma is controversial." (PMID 34596344, 2021). "This was a retrospective cohort study of 80 ALK‐rearranged lung adenocarcinoma patients who had undergone radical surgery and another 3031 ALK mutation‐negative patients were retrospectively reviewed for inclusion in this case‐controlled analyses." (PMID 34596344, 2021). "For instance, EGFRL858R/exon19Δ predicts a high propensity of bone and pleura metastases in a group of treating naïve patients with lung adenocarcinoma in late IV stage, while tumour cells with ALK rearrangement are more prone to metastasize to the liver." (PMID 34021647, 2021). "Here, we report a case of ALK-positive lung adenocarcinoma with meningeal carcinomatosis in which lorlatinib was used after resistance to alectinib and brigatinib." (PMID 34596160, 2021). "In conclusion, ALK rearrangement was an independent favorable prognostic predictor for OS in patients with completely surgically‐resected lung adenocarcinoma." (PMID 34596344, 2021). "Regarding histology, ALK rearrangements are typically detected in lung adenocarcinomas with solid growth predominance." (PMID 33435440, 2021). "We hope that our research can be verified in larger studies in the future and ultimately improve the clinical treatment of patients with ALK‐positive lung adenocarcinoma." (PMID 34596344, 2021). "Patients with ALK‐positive completely surgically‐resected lung adenocarcinoma have unique clinical features compared with other lung adenocarcinoma patients, including younger age, less are smokers, higher tumor stage and higher nodal stages." (PMID 34596344, 2021). "Positive PD-L1 expression was associated with unfavorable clinical outcomes in patients with ALK-positive lung adenocarcinoma receiving crizotinib." (PMID 34660278, 2021). "Various ALK fusion genes have been reported for anaplastic large cell lymphomas, inflammatory myofibroblastic tumors, and lung adenocarcinomas." (PMID 34559836, 2021). "Previous studies have revealed that the clinical characteristics of ALK‐positive lung adenocarcinoma are unique, including younger, more non‐smokers, more patients with adenocarcinoma, and more female patients." (PMID 34596344, 2021). "Third, ALK rearrangements are almost always mutually exclusive with other driver mutations, such as EGFR and KRAS mutations in lung adenocarcinoma." (PMID 33738250, 2021). "The Lungscape project reported that ALK rearrangement is a favorable factor in resected lung adenocarcinoma patients, and a meta‐analysis also predicts better prognosis in NSCLC patients." (PMID 34596344, 2021). "In recent years, to detect LN metastases, increased research with gene markers, such as anaplastic lymphoma kinase (ALK) in patients with clinical N0 lung adenocarcinoma has been proposed." (PMID 34031529, 2021). "Workup including chest computed tomography (CT), pathological examination of a biopsy specimen, and next-generation sequencing was consistent with a diagnosis of IVA ALK-rearrangement lung adenocarcinoma." (PMID 34190169, 2021). "Previous studies have indicated that the characteristics of ALK‐positive lung adenocarcinoma are different from other lung adenocarcinoma." (PMID 34596344, 2021).